TFAP2A (transcription factor AP-2 alpha)
Diseases named in the same sentence as TFAP2A in open-access papers (continued):
Sharing a sentence is not in itself a finding about the gene and the disease.
tumor (continued). "The clinical expression of AP-2α in CCA was also estimated, and upregulated levels of AP-2α was found in tumor samples when compared to normal tissues, thereby suggesting that miR-200b could directly target TFAP2A, and downregulation of miR-200b might participate in the tumor metastasis via TFAP2A." (PMID 29084594, 2017). "Our findings suggest that TFAP2A isoforms may be differentially regulated during breast tumourigenesis and this, coupled with differences in their transcriptional activity, may impact on tumour responses to tamoxifen therapy." (PMID 21375726, 2011). "In tumor cells, PRMT3 mediated arginine methylation of transcription factor TFAP2A, enhancing its binding to the indoleamine 2,3-dioxygenase 1 (IDO1) promoter." (PMID 41129671, 2026). "Transcription factor AP-2 alpha (TFAP2A) can affect a variety of biological processes and play a crucial role in driving tumorigenesis and tumor development." (PMID 40813717, 2025). "Given the apparent involvement of TFAP2A in the MAPK pathway, the impact of TFAP2A overexpression on the responsiveness of tumour cells to osimertinib, a first-line targeted drug for NSCLC patients, was investigated." (PMID 39695171, 2024). "Through functional experiments, we found TFAP2A promotes proliferation and migration of TNBC cells, and the tumor-suppressive effects of miR-8072 in TNBC are mediated through post-transcriptional downregulation of TFAP2A." (PMID 38890750, 2024). "The expression of Ifng, perforin (Pfr) and Gzmb was increased in Tfap2a-overexpressing B16F10 tissues, indicating the stimulation and antitumor immunity of tumor-infiltrating CD8+ T cells." (PMID 37330579, 2023). "Among the most overexpressed genes in tumor cells compared to normal tissue were the transcription factors HOXB9, SIM2, ZIC5, SP8, TFAP2A, FOXE1, HOXB13, and SALL4; the cancer testis antigen CT83; and the cytokine IL23A." (PMID 37228492, 2023). "Tfap2a-overexpressing stable B16F10 cells were inoculated subcutaneously into randomized BALB/c mice, Tfap2a suppressed tumor size." (PMID 37330579, 2023). "In terms of immune microenvironment remodeling, several bioinformatic studies have investigated the potential role of TFAP2A in regulating the extracellular matrix (ECM) and tumor immune microenvironment." (PMID 37291585, 2023). "IHC staining revealed that Tfap2a decreases Pdl1 expression but improves the density of Cd4+ and Cd8+ T cells in B16F10 tumor cells." (PMID 37330579, 2023). "Univariable analysis showed that age, molecular subtype, tumor TNM staging, TFAP2A, TFAP2B, TFAP2C and TFAP2E were important factors affecting the survival of BLCA patients." (PMID 37859819, 2023). "In endometrial carcinoma, TFAP2A transcriptionally induces small nucleolar RNA host gene 16 (SNHG16) expression by binding to the promotor, leading to tumor growth and glycolysis." (PMID 37291585, 2023). "Interaction between SRY-box transcription factor 8 (SOX8) and TFAP2A increases Golgi phosphoprotein 3 (GOLPH3) promoter activity and tumor growth of tongue squamous cell carcinoma." (PMID 37291585, 2023). "Previous studies have shown that TFAP2A and TFAP2C have inhibitory effects on tumor growth in a variety of tumors 6-8." (PMID 37859819, 2023). "This study proved that the inhibition of miR-3960 on PC via the TFAP2A/PTEN/AKT pathway and provides the ideas and methods to study the biological mechanism of exosomes in promoting tumor development and treatment of PC." (PMID 36284637, 2022). "Based on TCGA normal and GTEx database, the expressions of these genes in PC were analyzed, and the levels of PEG10, TFAP2A and EGR3 was remarkably greater in tumor compared to normal group (P <0.01)." (PMID 36284637, 2022). "Our findings suggest PPARɣ inactivation, as well as TFAP2A and TFAP2C overexpression cooperate with other TFs to promote the basal-squamous transition during tumor progression." (PMID 31772149, 2019).
tumor (continued). "In vivo tissue recombination studies show TFAP2A and TFAP2C promote tumor growth in line with the aggressive nature of basal-squamous bladder cancer." (PMID 31772149, 2019). "Because of the close association between TFAP2A and TFAP2C expression and the aggressive basal-squamous subtype, as well as their association with lymph node metastasis and distant recurrence in our tumor cohort, we hypothesized these transcriptional regulators may promote disease aggressiveness." (PMID 31772149, 2019). "Both TFAP2A and TFAP2C hold distinct roles as oncogenes or tumor suppressors in various tumor models." (PMID 30824562, 2019). "In some case high DCBLD2/ESDN expression coincided with very low levels of TFAP2A in tumor cells, while in other cases DCBLD2/ESDN high or low expression co-existed with high TFAP2A expression." (PMID 20525283, 2010). "Through a comprehensive workflow combining H3K27ac-ChIP-seq and RNA-seq analyses, we identified critical TFs and tumor-specific super-enhancer domains (T-SEDs) that regulate gene expression in HPV+ HNSCC, such as TP63, SMAD3, FOSL2, JUND, JUNB, KLF5, and TFAP2A." (PMID 41323280, 2025). "CAFs, one of the most prevalent cell types in the tumor microenvironment of PDAC, could upregulate the expression of TFAP2A through BMP4." (PMID 40727938, 2025). "Tfap2a could increase the cytotoxic effect of Cd8+ T cells in CT26, B16F10, and GL261 tumor-immune models, improve anti-tumor immunity, and promote the efficacy of anti-PD-1 therapy." (PMID 37330579, 2023). "Among the most overexpressed genes in tumor cells compared to normal tissue are genes coding for transcription factors (HOXB9, SIM2, ZIC5, SP8, TFAP2A, FOXE1, HOXB13, and SALL4), cancer testis antigens (CT83), and cytokines activating regulatory Th17 cells (IL23A)." (PMID 37228492, 2023). "Among these genes, six (HOXA6, STC2, HSD17B8, TFAP2A, CYP1B1, and HOXC8) were reported to be osteogenesis-/chondrogenesis-related genes, and five (ADRA1A, TSPYL5, TES, TNFRSF10D, and MBP) were reported to be tumor-suppressor genes." (PMID 31889115, 2019). "Two months following implantation, T24-EV xenografts were weakly tumorigenic and tumor volume was not significantly increased following TFAP2A overexpression (p = 0.2343; quantified in 8i)." (PMID 31772149, 2019). "A total of 56 molecules are annotated as affecting neoplasia and eight of these are dysregulated over 1.5 fold in Ad12-TC compared to Ad5-TC: down-regulation of ATM, CD19, CD3G, GADD45B, HPSE, TFAP2A and TFPI was observed, whereas levels of EGFR were found to be up-regulated." (PMID 19200380, 2009). "Besides, the RT-qPCR and western blot results demonstrated that TFAP2A was highly expressed in tumor tissues compared with the normal tissues." (PMID 40813717, 2025). "In summary, the present study revealed that TFAP2A promotes NSCLC progression by mediating ESR2 and subsequently activating MAPK signalling pathways, and combined treatment with the ESR2 inhibitor TPHPP and targeted therapy synergistically inhibits tumour growth and improved patient prognosis." (PMID 39695171, 2024). "The negative relationship between TFAP2A in most cancer types indicated that TFAP2A may play a crucial role in tumor immune escape." (PMID 38265973, 2024). "Following that, we explored the relationship between TFAP2A expression with Immune checkpoint (ICP) genes, immune subtypes, immune cell infiltrations, immunotherapy efficacy, and PD-L1 expression in cancer cell lines to unravel the role of TFAP2A from the perspective of tumor immunity." (PMID 38265973, 2024).
tumor (continued). "For PD, we identified 115 TFs, TFBSs for three of which were significantly enriched in tumor-specific PDs: FOSL2, JUND, and TFAP2A, whereas no significant enrichment was found in normal-specific PDs." (PMID 41323280, 2025). "A better comprehension of the TFAP2A-driven regulation of the DCBLD2/ESDN gene should provide novel and useful insights on mechanisms of tumor progression and metastasis formation." (PMID 20525283, 2010).
cancer (75 papers, 2005 to 2026). A tumor composed of atypical neoplastic, often pleomorphic cells that invade other tissues. "Cancer associated fibroblasts (CAFs) upregulated TFAP2A expression by bone morphogenetic protein 4 (BMP4)." (PMID 40727938, 2025). "Regarding TFAP2A, in several cancers, elevated TFAP2A expression is linked to enhanced proliferation, migration and invasion abilities." (PMID 37291585, 2023). "Transcription factor activator protein-2 alpha has been suggested as a candidate tumour suppressor protein, as loss of TFAP2A protein in several human cancers is associated with enhanced tumorigenicity." (PMID 19200380, 2009). "The most altered type of TFAP2A was amplification, which may be one of the causes of the increase of TFAP2A mRNA expression in cancer." (PMID 38265973, 2024). "In roughly half of cancer types, TFAP2A expression was strongly linked to a poorer prognosis." (PMID 38265973, 2024). "Based on these findings, we have developed a working model of how SUMO conjugation of the TFAP2A transcription factor alters patterns of gene expression associated with the transition of cancer cells from the more differentiated phenotype to the CSC/TIC subtype." (PMID 29383121, 2017). "Loss of function of TFAP2A in cancer cells could be due to hypermethylation of the CpG island from the human TFAP2A, which strongly correlates with decreased expression of the gene in neoplastic breast epithelial cells." (PMID 19200380, 2009). "It means that the TFAP2A may result in metastasis which is the main cause of cancer-related death." (PMID 36765073, 2023). "In addition, RNASeq analysis showed that curcumin treatment inhibited the oncogenic TFAP2A-mediated ECM pathway by negatively regulating the associated genes, including COMP, LAMA5, and ITGA1, wherein TFAP2A expression is associated with poor prognosis in cancer patients." (PMID 34681206, 2021). "Consistently, TFAP2A enhanced the protein levels of cancer stem cell markers and stemness-related genes, including CD44, CD133, NANOG, OCT-4A and SOX2." (PMID 40727938, 2025). "TFAP2A significantly regulates cancer biology by influencing cell proliferation, differentiation, and survival." (PMID 41323280, 2025). "For the first time, it is found that natural compound coptisine can stabilize the ATF4‐G4 and subsequently disrupt its interaction with transcription factor TFAP2A, ultimately restoring the effectiveness of glutamine‐restricted cancer therapies." (PMID 38994891, 2024). "It was interesting to note that TFAP2A mRNA expression in cognate cancer tissues was higher, whereas better outcomes in patients bearing high TFAP2A expression in some cancer types." (PMID 38265973, 2024). "In this study, we focused our study on the involvement of TFAP2A in pan-cancer to identify its common functional roles." (PMID 38265973, 2024). "On the contrary, in the other small fraction of cancer types, TFAP2A mRNA expression was significantly lower, including KIRC, and KIRP." (PMID 38265973, 2024). "The IHC images showed that the protein expression levels of TFAP2A in several cancer types were higher, which was in accordance with the mRNA levels from other databases." (PMID 38265973, 2024). "Although several studies have reported that TFAP2A promoted cancer progression by regulating different pathways, the common function of TFAP2A in pan-cancer has rarely been analyzed systematically." (PMID 38265973, 2024). "TFAP2A expression was tissue-specific in various cancer cell lines, especially overexpressed in the breast, prostate, skin in mRNA levels, and upper in aerodigestive, uterus, esophagus in protein levels." (PMID 38265973, 2024). "The presence of a binding site in the OTUB1 promoter for TFAP2A suggested an enhanced overexpression of OTUB1 when high levels of TFAP2A are detectable in cancer cells." (PMID 37132605, 2024). "ESTIMATEScore, ImmuneScore, and StromalScore indicated that TFAP2A expression was negatively relevant to 12 out of 16 cancers." (PMID 38265973, 2024).
cancer (continued). "In order to get further understanding of the common functions of TFAP2A in pan-cancer, we performed enrichment analysis of co-expressed and differentially expressed genes with TFAP2A in pan-cancer and collated the data." (PMID 38265973, 2024). "In this study, we first analyzed the expression of TFAP2A, and its prognosis values, genomic alternations in pan-cancer." (PMID 38265973, 2024). "Because of the differences across intra-tumoral heterogeneity of human cancers, TFAP2A has paradoxical effects on different kinds of carcinomas." (PMID 38265973, 2024). "Taken together, this study highlighted the potential role of TFAP2A in pan-cancer, hence offering a novel and promising insight into prognosis and immunotherapy." (PMID 38265973, 2024). "In the case of LUSC, the situation is opposite and higher expression of the TFAP2A gene correlates with cancer cells (p = 0.012)." (PMID 36831334, 2023). "Especially, the positive role of TFAP2A in cancer cell proliferation was frequently revealed in recent years." (PMID 36707053, 2023). "The role of DLGAP2 and CCDC144A in malignant tumors is still unclear, but previous studies have suggested that TFAP2A can promote or inhibit cancer progression in tumors." (PMID 38125697, 2023). "SUMO inhibitors with SUMO-unconjugated TFAP2A reduce the cancer stem cell (CSC) population by suppressing CD44 and matrix metallopeptidase 14 (MMP14) expression to limit the stemness." (PMID 37291585, 2023). "Numerous scientific reports describe differential expression of these TF and their genes in various types of cancer, identifying among them a potential oncogene or suppressor like TFAP2A or TFAP2C." (PMID 36831334, 2023). "Despite enormous advances achieved in cancer development, the mechanism by which TFAP2A promotes cancer development has yet to be elucidated." (PMID 36707053, 2023). "In clinical specimens, we also validated cancer-regulating effect of miR-16 family/TFAP2A/PSG9 axis, especially for lymph node metastasis of LUAD." (PMID 33824285, 2021). "Uncontrolled proliferation remains the preliminary characteristic for cancer, we first investigated effect of TFAP2A upon LUAD proliferation." (PMID 33824285, 2021). "TFAP2A mainly functions as a transcription factor, so its cancer-mediating effect largely attributes to critical transcriptional targets." (PMID 33824285, 2021). "In the present study conducted on cancer tissue, we confirm the significance of TFAP2A, as its higher expression in cancer tissues in contrast to normal ovary was noted." (PMID 31362717, 2019). "For TFAP2A, a total of 4 of 7 malignant cases showed positive staining for TFAP2A, and 2 of 7 adjacent non-cancer tissue samples were positive." (PMID 30177858, 2018). "Altogether, this is an interesting manuscript yet requiring a few modifications and clarifications to convincingly argue in favor of TFAP2A’s role in cancer progression." (PMID 28412966, 2017). "Overall, our data links TFAP2A to the core TF network that is regulating EMT in normal development as well as in cancers." (PMID 28412966, 2017). "The role of TFAP2A in cancer progression appears to vary according to cancer type and remains to be determined in OCCC development." (PMID 28611940, 2017). "Our data thus connects TFAP2A to the core regulatory network that orchestrates the epithelium-to-mesenchyme transition in normal development as well as in cancers." (PMID 28412966, 2017). "We screened genes co-expressed with TFAP2A in 33 cancers, then estimated whether the genes co-expressed with TFAP2A in more than one half of cancer types." (PMID 38265973, 2024). "Furthermore, TFAP2A mRNA and protein levels in tissue-derived cancer cell lines were examined according to the CCLE database." (PMID 38265973, 2024). "Taken together, TFAP2A has higher expression levels in most types of cancer." (PMID 38265973, 2024). "To understand TFAP2A genetic alterations in pan-cancer, we explored the cBioPortal database." (PMID 38265973, 2024).